BRAF (B-Raf proto-oncogene, serine/threonine kinase)
Diseases named in the same sentence as BRAF in open-access papers (continued):
Sharing a sentence is not in itself a finding about the gene and the disease.
melanoma (continued). "Adjuvant treatment with targeted therapy was not restricted to patients with melanoma with BRAF V600E or V600K mutations (as in the Combi-AD trial)." (PMID 37686659, 2023). "In chemotherapy, some of the commonly used agents are dacarbazine, temozolomide, lomustine, and vinorelbine, whereas targeted therapy, which is currently considered the first-line treatment option for melanoma, includes BRAF inhibitors such as vemurafenib, dabrafenib, and cobimetinib." (PMID 36649046, 2023). "Currently, combined TT is the standard of care for BRAF-mutant melanoma patients, and the response rates with TT rechallenge in clinical practice may be somewhat lower than what was reported in this paper." (PMID 37568570, 2023). "Most advance and successful examples include targeting BCR-ABL with imatinib in chronic myeloid leukemia, inhibiting EGFR with cetuximab in colorectal cancer, antagonizing BRAF with vemurafenib in melanoma, and inhibiting multiple tyrosine kinases with lenvatinib in hepatocellular carcinoma." (PMID 37427373, 2023). "These investigators further confirmed that the enhanced anti-proliferation effect mediated by CQ and LY are not related to BRAF-activating mutations (BRAF-activating mutations occur in 50–70% of melanoma cases) as shown by real-time PCR analysis." (PMID 36831202, 2023). "We retrospectively collected data of Asian patients with advanced BRAF V600‐mutant melanoma treated with first‐line BRAF/MEK inhibitors (BRAF/MEKi), anti‐PD‐1 monotherapy (Anti‐PD‐1), and nivolumab plus ipilimumab (PD‐1/CTLA‐4) between 2016 and 2021 from 28 institutions in Japan." (PMID 37584204, 2023). "Indeed, BRAF-mutated melanoma cells can be effectively targeted by RSK inhibition and its family members RSK1 and RSK2 have been reported to enhance melanoma cell survival under chemotherapy." (PMID 37464364, 2023). "Despite the clear outcome benefits from targeted therapies for BRAF-mutated melanoma in other regions, there is no clear path to prepare LA for a sustainable personalized medicine approach to this disease." (PMID 36998456, 2023). "Furthermore, melanoma patients with tandem mutation in BRAFV600; K601 were less responsive to combined BRAF/MEK inhibitors." (PMID 37205993, 2023). "Still, a few studies have documented BRAF-related melanoma in LA." (PMID 36998456, 2023). "BRAF and NRAS mutations have been identified in 50% and 8% of melanoma, respectively." (PMID 36982192, 2023). "The presence of BRAF V600E mutation in nevus melanocytes, which have not evolved into melanomas, is associated with cell cycle arrest due to a protective mechanism known as oncogene-induced senescence." (PMID 37627054, 2023). "Furthermore, the activation of other signalling pathways such as the tumour necrosis factor alpha (TNF-α)/nuclear factor kappa B (NF-kB) pathway enhances melanoma cell growth, and contributes to the failure of chemotherapy treatment including BRAF inhibitors." (PMID 36678596, 2023). "This pathway endows resistance to BRAF inhibition in melanoma, colorectal, and glial tumor cells." (PMID 38045829, 2023). "The number of melanoma driver gene mutations did not significantly differ according to response to therapy, although in the BRAF V600+ subset, the median number of melanoma driver gene mutations in NR was twice that in R." (PMID 36901733, 2023). "This study suggests that, for patients with melanoma brain metastases, BRAF status may be an important molecular biomarker to guide systemic therapy selection." (PMID 37589977, 2023). "Notably, erianin suppressed BRAF V600E or RAS mutant melanoma and colorectal cancer cell by inhibiting MEK1/2 and CRAF but not BRAF kinase activity." (PMID 36872366, 2023). "Specifically, Bradley and colleagues reported that oncogenic BRAF activation causes an altered surface expression of MHC-I molecules (and subsequent reduction in CD8+ T-cell recognition of melanoma cells) due to their rapid internalization and subsequent sequestration within endolysosomes." (PMID 37627054, 2023).
melanoma (continued). "Notably, most patients in this study (77%) had BRAF wild-type melanoma, and the trial statistics focused on this population." (PMID 37404764, 2023). "Several in vitro melanoma cell lines are characterized by the BRAFV600E mutation, and, in the present analysis, we took advantage of the 1205Lu human line, which is characterized by this BRAF variant." (PMID 36672229, 2023). "Briefly, 37 patients (53%) were males, the median age was 61 years (range, 27–91 years), 19 (24%) patients had brain metastases, 59 (76%) had BRAF wild-type melanoma and 16 (21%) had BRAF mutations, while BRAF status was not known for 3 patients." (PMID 37684649, 2023). "Notably, after treatment with nivolumab and ipilimumab, melanoma patients with BRAF mutant had significantly higher OS at five years than those without BRAF mutation (60% vs. 48%), suggesting that the immune microenvironment of BRAF-mutant melanoma may be distinct from that of wild type melanoma." (PMID 37205993, 2023). "However, it is important to understand anti-CTLA-4’s mechanistic contribution to combination anti-PD-1/CTLA-4 therapy and investigate anti-CTLA-4 therapy for BRAF-wild type melanoma cases reresected after previous adjuvant anti-PD-1 therapy." (PMID 36980641, 2023). "One mutation, BRAF p.Val600Glu, showed significant age differences: mutation carriers were diagnosed with melanoma on average 9 years earlier than those without (padj = 7.58 × 10−6)." (PMID 37339630, 2023). "Interestingly, two melanomas carried the PPP6C R264C variant, which has been reported to have a unique role in melanocytes and melanoma cells, co-occurring with the BRAF V600K substitution." (PMID 36765773, 2023). "Additionally, the insulin-like growth factor-1 (IGF-1R) can contribute to BRAF resistance to targeted therapies in melanoma." (PMID 37174072, 2023). "Demonstrating a general responsiveness of melanoma cells to ERK inhibition, both BRAF-mutated and BRAF-WT cells responded with strong loss of cell viability to combination treatments with SCH772984/S63845 (A-375, 8%; Mel-HO, 11%; MeWo, 17%; SK-Mel-23, 7%; 10 μM SCH772984/1 μM S63845; 48 h)." (PMID 36902392, 2023). "Also, further investigation should be necessary to understand the synergize potential of STX140 with other melanoma drug therapies used in clinics (such as BRAF and MEK inhibitors)." (PMID 37511073, 2023). "A BRAF-sensitive melanoma cell line (WM164) treated with BRAF inhibitor in the presence of CSF from LMM patients with a poor prognosis efficiently protected melanoma cells from apoptosis." (PMID 36980770, 2023). "Given the significant differences in microenvironmental composition of both adaptive and innate immune cell populations based on BRAF status, we next examined how BRAF alteration status in melanoma brain metastases correlated with response to ICI immunotherapy." (PMID 37589977, 2023). "Thus, BH3 mimetics for targeting Bcl-2, Bcl-xL, and Bcl-w (ABT-737, -263, -199) have been developed, and their combination with vemurafenib has resulted in enhanced apoptosis and reduced cell viability in BRAF-mutant melanoma cells." (PMID 36902392, 2023). "It was acknowledged that BRAF mutation did not affect the benefit melanoma patients got from anti-PD-1 treatment." (PMID 36747118, 2023). "Current targeted therapy agents for melanoma aim to block BRAF and MEK proteins." (PMID 37513949, 2023). "Additionally, given the importance of BRAF signalling in melanoma pathogenesis, can blebs contribute to therapy resistance?" (PMID 38162121, 2023). "More recently, the DREAMseq trial (EA 6134) confirmed that initial ICI treatment with ipilimumab/nivolumab produced superior progression-free and overall survival, as well as improved response duration, compared to initial therapy with dabrafenib/trametinib in patients with BRAF mutant melanoma." (PMID 37444637, 2023).
melanoma (continued). "BRAF mutations, MEK mutations, and programmed cell death protein-1 (PD-1) are specific gene or protein receptor targets that have significantly changed the overall survival (OS) of patients with advanced-stage melanoma." (PMID 37504313, 2023). "HLA-DR was detected at low, medium, and high levels in melanocytes, primary melanoma, and metastatic melanoma cells, respectively, although these biopsies contained BRAF and not the NRAS mutation, which is associated with higher HLA-DR expression." (PMID 37563418, 2023). "Here, we employ inducible AKT-isoform-specific shRNAs and CRISPR/Cas9-mediated gene editing in human melanoma cell lines to outline the role of AKT2 in the metastatic cell seeding of oncogenic BRAF-driven PTEN-null melanoma through the enhancement of cell migration and invasiveness." (PMID 37894325, 2023). "A potential explanation for this finding it that as the NRAS and BRAF genes are both involved in the MPAK pathway, activating mutations of the NRAS gene in BRAF-wild type melanoma or the BRAF gene in BRAF-mutant melanoma may lead to a similar phenotype." (PMID 36836460, 2023). "In fact, unlike the Caucasian population, Asian melanoma patients have a relatively low frequency (about 20%) of BRAF mutations." (PMID 37627054, 2023). "Furthermore, in BRAF-mutant melanoma cells, the increased activity of the MAPK pathway results in the inhibition of the genetic programme regulated by TFEB, leading to tumour progression and chemoresistance to BRAF inhibitors." (PMID 37160873, 2023). "Besides, BRAF and CRAF collaborate to activate ERK and maintain proliferation in NRAS-mutated human melanoma cell lines." (PMID 38111008, 2023). "We showed that ICI strengthens the ability of circulating EVs to impact on the metastatic potential of melanoma cells mainly in BRAF wt ones, increasing their invasive and migration ability towards the metastatic niche, in the formation of which macrophages play a key role." (PMID 37759291, 2023). "This chromosome loop was further confirmed via the chromosome conformation capture (3C) assays on A375, SK-MEL-28 (another BRAFV600E melanoma cell line), and SK-MEL-2 (no BRAF mutation melanoma cell line) cells at different conditions." (PMID 37904237, 2023). "Then, melanoma cells were treated with BRAF and MEK inhibitors plus EVs (daily added) for 72 h." (PMID 37174717, 2023). "Overexpression of miR-211 in melanoma cells induces their resistance to BRAF and MEK inhibitors, which is associated with an increase in the phosphorylated fraction of ERK5 effectors of a MAPK pathway other than BRAF." (PMID 37174072, 2023). "In hereditary forms of melanoma, which represent about 10% of melanomas, no BRAF mutations have ever been described to date." (PMID 37627054, 2023). "On the hand in conventional melanomas, resembling Spitz tumors or not, the initiating event is the involvement of BRAF, NRAS, KIT or NF1 mutations." (PMID 38031947, 2023). "In melanoma cells, enhanced caspase-3 activation and mitochondrial activation have been reported in response to combinations of S63845 or TW-37 (targeting Mcl-1, Bcl-xL and Bcl-2) with BRAF inhibitors (vemurafenib or encorafenib)." (PMID 36902392, 2023). "While targeted therapies against B-Raf proto-oncogene (BRAFV600) and its downstream target mitogen-activated protein kinase kinase 1/2 (MEK1/2) are beneficial for patients with BRAF mutant unresectable melanoma, acquired resistance remains a fundamental clinical challenge." (PMID 37835493, 2023). "Our results may inform the clinical trial design to understand the potential mechanisms of drug resistance to BRAF inhibitors in melanoma patients." (PMID 37205993, 2023). "Aberrant activation of the BRAF kinase occurs in approximately 50% of melanomas." (PMID 36768978, 2023). "Following BRAF, NRAS, and NF1 comprise the next most common mutations identified in melanoma." (PMID 37900283, 2023).
melanoma (continued). "A phase I/II dose escalation study combining afuresertib with trametinib in patients with advanced solid tumours observed a partial response in a patient with BRAF-wild-type melanoma, however the combination therapy was poorly tolerated with extensive adverse effects recorded [NCT01476137]." (PMID 37181747, 2023). "The advanced BRAF-mutant melanoma adaptive trial (NCT03543969) administers Encorafenib (a small molecule BRAF-inhibitor) and Binimetinib (a selective MEK inhibitor) in combination adaptively, with Nivolumab (an immune checkpoint inhibitor that blocks PD-1) administered continuously." (PMID 36952376, 2023). "Interestingly, a study conducted in a PDX model of BRAF mutant melanoma demonstrated that NCSC depletion from MRD prevented the development of non‐genetic mechanisms of acquired resistance, leaving persistent cells dependent on de novo genetic mechanisms." (PMID 36967556, 2023). "The phase I/II clinical trial KEYNOTE-022 enrolled 120 subjects with unresectable locally advanced or metastatic BRAF V600E- or V600K-mutant melanoma who were randomly assigned to be treated with dabrafenib 150 mg BID and trametinib 2 mg daily combined with pembrolizumab 200 mg 3-weekly or placebo." (PMID 36995534, 2023). "Common examples are HER2 in breast and gastric cancers, EGFR in lung, colorectal, and head and neck cancers, KRAS in colorectal, pancreatic, and lung adenocarcinoma, BRAF in melanoma and colorectal cancer, ALK in some NSCLC cases, and PSA as a prostate cancer biomarker." (PMID 38202898, 2023). "Interestingly, depletion of TCF12 can sensitize melanoma to BRAF inhibition both in vitro and in vivo." (PMID 37760480, 2023). "To test the hypothesis that tumor alterations are associated with clinical outcome, we next examined the full cohort of 94 patients with resected melanoma brain metastases with targeted BRAF assessment." (PMID 37589977, 2023). "In melanoma, preclinical evidence revealed that niclosamide inhibited melanoma cell proliferation in vitro, independent of BRAF or NRAS mutation status, inhibiting tumour growth in xenograft models by uncoupling mitochondria and increasing metabolic stress." (PMID 37181747, 2023). "TTs have revolutionized the treatment landscape of advanced BRAF mutant melanoma." (PMID 36967556, 2023). "Among all cell lines tested in this study, FGFR1 was highly expressed in EGFR + NSCLC NCI-H1650, HCC827, NCI-H1975, and HER2 + BC HCC1569 cells and BRAF+melanoma RPMI-7951, IGR-39, and SK-MEL-3 cells, and FGF2 was highly expressed in NCI-H1650, HCC827, HCC1569, RPMI-7951, and IGR-39 cells." (PMID 37880373, 2023). "Interestingly, aging has been reported to impact melanoma metastasis and sensitivity to BRAF-targeted therapies." (PMID 37174072, 2023). "Such a model may help further understand the BRAF gene's role in melanoma pathogenesis and improve the OS rate of melanoma patients." (PMID 37205993, 2023). "While CRAF expression may differ in various types of BRAF mutant melanomas (BRAFV600E or non-BRAFV600E), it is worth noting that increased CRAF levels have been reported to promote resistance in a subset of BRAF mutant melanomas." (PMID 38111008, 2023). "Remarkably, the NCSC-like cellular state in BRAF-mutated melanoma has also been associated with the development of non-genetic resistance to MAPK-targeted therapies in a NGFR/FAK/AKT-dependent manner." (PMID 36774337, 2023). "It has been tested in several homozygous melanoma cell lines for BRAF V600E." (PMID 38136350, 2023). "However, in BRAF-mutant melanoma, the prolonged use of vemurafenib or other BRAF inhibitors would lead to drug resistance." (PMID 37089937, 2023). "In BRAF mutant melanoma resistant to BRAFi and MEKi, IGF1R activation induces ERK5 phosphorylation." (PMID 37420093, 2023).
melanoma (continued). "Interestingly, BRAF mutant CRCs exhibit elevated levels of phosphor-EGFR compared to BRAF mutant melanomas." (PMID 38111008, 2023). "As TERT alterations are common in BRAF V600 mutant melanomas and plays an important role in controlling the apoptosis of cancer cells, combined therapies targeting both BRAF and TERT may potentially improvement the survival of these patients." (PMID 37239381, 2023). "BRAF is dominant among the three isoforms of RAF, and the BRAFV600 mutations are present in approximately 8% of human tumors, with activating somatic mutations of BRAF in 40–66% of melanomas." (PMID 37370834, 2023). "For example, it is still controversial whether adjuvant anti‐PD‐1 monotherapy or BRAF/MEK inhibitors may better improve the survival for resected BRAF‐mutant melanoma." (PMID 37403699, 2023). "Additionally, combining cIAP1/2 inhibitors with BRAF/MEK inhibitors delayed the onset of acquired resistance in melanomas in vivo." (PMID 38132479, 2023). "After pre-treatment with 5 μM vemurafenib, we observed a significant reduction in cell viability when combined with CBD 6 μM and THC 15 μM, suggesting that cannabinoids might be able to resensitize some melanoma cells for BRAF inhibitor therapy." (PMID 37237519, 2023). "Noteworthy, this effect was more pronounced in WTBRAF melanoma cells compared to BRAF mutant cells." (PMID 37508519, 2023). "Advanced BRAF malignant tumors – melanoma, colorectal, NSCLC, thyroid." (PMID 37645429, 2023). "Some of these secreted growth-promoting factors were identified in a similar study in the secretome of BRAF inhibitor-resistant melanoma cells, where endothelin-1 was identified as a molecular factor contributing to paracrine protection of resistant cells from BRAF inhibition." (PMID 37106808, 2023). "We devised a strategy based on CRISPR-Cas9 knockout of endogenous MC1R in a human melanoma cell line wildtype for BRAF, NRAS and NF1, followed by reconstitution with epitope-labeled MC1R constructs, and functional analysis of clones expressing comparable levels of wildtype, R151C or D294H MC1R." (PMID 37762683, 2023). "CRAF and A- raf (ARAF) protooncogene isoforms have been observed in melanoma, which could cause MAPK pathway activation once BRAF is inhibited and cause BRAF-i resistance." (PMID 37645429, 2023). "This study explores the therapeutic effect of the combination of BRAF and MEK inhibitors (BRAFi + MEKi) on NRAS-mutated melanomas in vitro, in preclinical in vivo models using patient-derived xenografts (PDXs) and in an individual healing attempt of one patient." (PMID 38067230, 2023). "ERK signaling in melanoma becomes independent of upstream feedback mechanisms because of mutations in BRAF and NRAS." (PMID 37370834, 2023). "Therefore, the functional relationship between BRAF, nevi, and melanoma needs to be clearly defined." (PMID 37627054, 2023). "Our approach for predicting melanoma progression leverages both proteomics results and gene expression datasets derived from different populations to yield interesting mechanistic insights on adaptive resistance to BRAF/MEK inhibitors in melanomas." (PMID 37176114, 2023). "However, despite the success of BRAF inhibitors in melanoma, there has been a less impressive response among patients with mCRC." (PMID 36900187, 2023). "Moreover, melanoma cells intrinsically resistant to or adapted to BRAF inhibition exhibit lower basal levels of mitochondrial biogenesis and addiction to oxidative phosphorylation, respectively." (PMID 37834284, 2023).